Y_RNA (Y RNA )
Gene: Miscellaneous RNA gene on chromosome 9 (32,820,261 to 32,820,350, forward strand). Ensembl gene ENSG00000272113.
Homologues: Orthologues: chimpanzee Y_RNA (100% identical), macaque Y_RNA (93% identical). Paralogues in human: Y_RNA (94% identical), RNY1 (93% identical), Y_RNA (92% identical), Y_RNA (91% identical), Y_RNA (90% identical), RNY1P11 (89% identical), RNY1P8 (89% identical), Y_RNA (89% identical), Y_RNA (88% identical), Y_RNA (87% identical), Y_RNA (86% identical), RNY1P10 (84% identical), and 100 more.